SIRT1 (sirtuin 1)
Diseases named in the same sentence as SIRT1 in open-access papers (continued):
Sharing a sentence is not in itself a finding about the gene and the disease.
endothelial dysfunction (continued). "In conclusion, cilostazol improves HG-induced endothelial dysfunction in vascular ECs and enhances angiogenesis in diabetic mice by upregulating the expression of adiponectin/adipoRs and its SIRT1/AMPK downstream signaling molecules." (PMID 36499166, 2022). "Cilostazol improves HG-induced endothelial dysfunction in vascular endothelial cells and enhances angiogenesis in diabetic mice by upregulating the expression of adiponectin/adipoRs and its SIRT1/AMPK downstream signaling pathway." (PMID 36499166, 2022). "Chronic TMS treatment alleviated endothelial dysfunction via enhancing the AMPK/SIRT1/eNOS pathway and attenuated oxidative stress and ER stress in aortas of diet-induced obese mice." (PMID 35883777, 2022). "We found that the activation of AMPK and SIRT1 was involved in the vaso-protective effect of TMS against high-glucose-induced endothelial dysfunction." (PMID 35883777, 2022). "The upregulation of miRNA-34a and miRNA-204, which impair SIRT1, and the reduction of miRNA-126, which plays a protective role in atherosclerosis, are involved in endothelial dysfunction in patients with DM and CAD." (PMID 35562979, 2022). "The sirtuin 1 (SIRT1) activator resveratrol has emerged as a promising candidate for the prevention of vascular oxidative stress, which is a trigger for endothelial dysfunction." (PMID 36499460, 2022). "SIRT1 can prevent high glucose-induced endothelial dysfunction by inhibiting oxidative stress in the vascular endothelium mediated through deacetylation of p66Shc." (PMID 34071497, 2021). "We discuss the contribution of endothelial inflammatory activation and dysfunction to atherogenesis and postulate that the dysregulation of specific epigenetic enzymes, EZH2 and SIRT1, aggravate endothelial dysfunction in a pleiotropic fashion." (PMID 33562658, 2021). "The previous investigations reveal that SIRT1 protects vascular endothelial cells against age‐related endothelial dysfunction, whereas little research explores the role of SIRT1 in the morphology and function of HSECs." (PMID 33522656, 2021). "Upregulation of miR-34a expression in mice leads to the occurrence of endothelial dysfunction by targeting SIRT1 expression, and overexpression of SIRT1 rescues miR-34a-induced endothelial dysfunction." (PMID 33802566, 2021). "As reported in scientific literature, resveratrol exerts many of its cardiovascular protective effects, especially against endothelial dysfunction, through the activation of Sirtuin-1 and AMPK." (PMID 34063322, 2021). "The activation of SIRT1 alleviated miR-34a-mediated endothelial dysfunction, inflammatory infiltration, and vascular damage, in a mouse model of LPS-induced lung injury." (PMID 33693011, 2021). "In this review, we will summarize the extensive evidence linking SIRT1 functional and quantitative defects to cellular senescence and aging, with particular regard to their role in determining endothelial dysfunction and consequent cardiovascular diseases." (PMID 34690807, 2021). "Hydroxytyrosol nitric oxide has been found to prevent endothelial dysfunction by decreasing ROS production and improving nitric oxide release mediated through an augmentation in SIRT1 expression in high glucose-exposed human umbilical vein endothelial cells." (PMID 34071497, 2021). "SIRT1 increases endothelial NO production by activating eNOS, leading to vasodilation and reversing endothelial dysfunction." (PMID 34746831, 2021). "Metformin can protect HG-induced endothelial dysfunction through regulating SIRT1 expression/activity directly or partly via LKB1/AMPK pathway." (PMID 33828486, 2021).
endothelial dysfunction (continued). "Previous studies showed that SIRT-1 expression or activity is reduced in people with T2D, GDM, or metabolic syndrome, which was also associated with endothelial dysfunction." (PMID 34149611, 2021). "Inhibitors causes endothelial dysfunction and increases NADPH oxidase–derived ROS in the vascular wall by impairing activities of SIRT1, leading to vascular aging." (PMID 33828486, 2021). "•SIRT1 increase endothelial NO production by activating eNOS leading to vasodilation reversal of endothelial dysfunction." (PMID 34746831, 2021). "Taken together, SIRT1 either enhances eNOS expression or eNOS enzymatic activity to protect against oxidative stress and endothelial dysfunction." (PMID 33304318, 2020). "Aspirin attenuates vinorelbine-induced PKC phosphorylation, NOX activation, and ROS production, subsequently preventing endothelial dysfunction via the SIRT1/AMPK axis." (PMID 33658920, 2020). "This relation between SIRT1 and NF-κB becomes a main concern when SIRT1 is inhibited exclusively in the endothelium, which has been demonstrated to represent an excellent model of global endothelial dysfunction." (PMID 32494847, 2020). "SIRT1, which decreases with age, is supposed to contribute to age-related endothelial dysfunction by compromising eNOS." (PMID 32796661, 2020). "Noteworthly, SIRT1 protects against endothelial dysfunction and slows down the progression of cardiovascular senescence." (PMID 32047577, 2020). "In the endothelial dysfunction animal model, the SIRT1 agonist resveratrol activates eNOS, enhances endothelial function, prevents elevated blood pressure, and restores vascular eNOS activity." (PMID 32082101, 2020). "NAR beneficial effects are attributable to its similarity to the natural structure of SIRT1 activator resveratrol, an enzyme involved in many physiological functions and reported to be depleted in endothelial dysfunction." (PMID 32630452, 2020). "Indeed, historically Sirt1 has been recognized as an enzyme crucial to assure lifespan prolonging from yeasts to humans, and, in general, its decreased levels have been linked to endothelial dysfunction and the pathogenesis of metabolic and cardiovascular diseases." (PMID 33238655, 2020). "Activation of the SIRT1/AMPK signaling in PVAT can beneficially regulate adipokine expression, ameliorate endothelial dysfunction caused by inhibiting NFκB activation, and alter PVAT inflammation induced by fructose- or HFD-feeding." (PMID 31572218, 2019). "Accordingly, SIRT1 has demonstrable protective effects against endothelial dysfunction through the prevention of the stress response, which is considered a target for the treatment of human pathologies such as diabetic complications." (PMID 31068817, 2019). "SIRT1 upregulation in these cells was found to be protective against glucose-induced endothelial dysfunction indicating its potential protective role in diabetic vascular complications." (PMID 29085333, 2017). "We then investigated if miR-204 is obligatory for vascular ER stress and endothelial dysfunction in EC Sirt1−/− mice." (PMID 28839162, 2017). "Another active compound tetramethylpyrazine (TMP) is isolated from a Chinese herb and is capable of reversing high glucose-induced endothelial dysfunction via upregulation of Sirt1." (PMID 28546854, 2017). "Here we show that microRNA-204 (miR-204) promotes vascular ER stress and endothelial dysfunction by targeting the Sirtuin1 (Sirt1) lysine deacetylase." (PMID 28839162, 2017). "It appears that SIRT1 also plays a protective role in preventing ROS production in endothelial cells, as activating SIRT1 pharmacologically prevents ROS-induced endothelial dysfunction." (PMID 26697131, 2016). "SIRT1 serves as an anti-atherosclerotic factor by mediating endothelial nitric oxide synthase (eNOS) and improving endothelial dysfunction, regulating inflammation, reversing cholesterol transport and reducing the risk of CAD." (PMID 27841908, 2016).
endothelial dysfunction (continued). "Among the genes targeted by miR-204 in the vascular wall is Sirt1, downregulation of which promotes endothelial dysfunction." (PMID 27586459, 2016). "Taken together, SIRT1 stands as a major protector against the progression of cardiovascular diseases which are triggered by endothelial dysfunctioning." (PMID 25907989, 2015). "This suggests a protective role of SIRT1 in preventing endothelial dysfunction, which is one of the resulting features of cellular senescence." (PMID 25907989, 2015). "In order to better elucidate the function of SIRT1 protein in the cardiovascular diseases, the other disease marker paramaters like levels of endothelial dysfunction and oxidative stress and their relation with SIRT1 protein level were also investigated." (PMID 24587358, 2014). "SIRT1 is highly expressed in the vasculature and acts as a key regulator of vascular endothelial homeostasis controlling angiogenesis, vascular tone and endothelial dysfunction." (PMID 24859347, 2014). "A SIRT1 upregulation and/or activation is associated with beneficial effects on ECs, while, excessive ROS or aging, decreases SIRT1 expression leading to endothelial dysfunction." (PMID 23975169, 2013). "Cell culture and animal studies have demonstrated that SIRT1 exerts protective effects against endothelial dysfunction by preventing stress-induced senescence and increasing eNOS mediated NO production." (PMID 24219792, 2013). "Recent studies have suggested that SIRT1 is a key regulator of vascular endothelial homeostasis controlling angiogenesis, vascular tone and endothelial dysfunction." (PMID 23284668, 2012). "Additionally, the SIRT1 activator SRT1720 has demonstrated efficacy in reversing endothelial dysfunction and vascular inflammation in a mice model, highlighting the critical role of the SIRT1-eNOS axis in vascular health." (PMID 40227195, 2025). "To investigate whether CHKA affects endothelial dysfunction through the NAD+‐SIRT1‐Notch axis, we employed a VEGF‐induced retinal vascular leakage model." (PMID 40548950, 2025). "Mechanistically, CHKA regulated endothelial dysfunction through the NAD+‐SIRT1‐Notch signaling." (PMID 40548950, 2025). "Despite the recent advances achieved in understanding the intricate interactions by which Sirt1 contributes to preventing vascular aging, many mechanisms related to Sirt1 protection against endothelial dysfunction are still far from being fully elucidated, thus requiring deeper insights." (PMID 39273039, 2024). "Moreover, SIRT1 prevents endothelial dysfunction via deacetylation of PGC-1α and PPARα, which reduces NADPH oxidase activity and improves NO activation." (PMID 38095615, 2023). "Therefore, there are well-documented reasons to treat the activation or inhibition of SIRT1 as a potential therapeutic target, especially in hypertensive disorders complicating pregnancy, in which the main pathomechanism is based on endothelial dysfunction." (PMID 38003402, 2023). "Overall, SIRT1 plays a crucial role in preserving endothelial function by regulating various cellular pathways that are involved in the development of endothelial dysfunction and has emerged as a potential therapeutic target for the prevention and treatment of cardiovascular diseases." (PMID 38304233, 2023). "The sirtuin 1 (SIRT1) enzyme plays a key role in the regulation of many physiological functions, and its reduced expression often causes aging-related diseases such as myocardial hypertrophy, myocardial infarction, and endothelial dysfunction." (PMID 37446644, 2023). "The study indeed suggested that endothelial CRIF1 is critical for preserving cardiac function and that SIRT1 induction could be a promising therapeutic approach for endothelial dysfunction-induced cardiac dysfunction." (PMID 38304233, 2023).
endothelial dysfunction (continued). "Its impact on BP in diet-induced hypertensive rats was associated with an improvement in both the oxidative stress, increasing hepatic reduced glutathione (GSH) levels, and in the endothelial dysfunction, downregulating Et-1 expression and upregulating Sirt-1 expression in aorta." (PMID 36678328, 2023). "Taken together, TMS treatment might activate the AMPK/SIRT1/eNOS pathway to enhance NO bioavailability and protect against high glucose-induced endothelial dysfunction." (PMID 35883777, 2022). "Likewise, the results from Western blotting suggested that TMS ameliorated high glucose-induced endothelial dysfunction via stimulating the AMPK/SIRT1/eNOS pathway and reducing ER stress." (PMID 35883777, 2022). "The present study was aimed at investigating the role of SIRT1 in reducing endothelial dysfunction and platelet aggregation in MTHFR CT subjects and in Mthfr+/– mice through the administration of pure trans-resveratrol (RSV), a SIRT1 activator by mimicking caloric restriction." (PMID 35821533, 2022). "SIRT1 protects endothelial dysfunction triggered by oxidative stress and inflammation." (PMID 36359987, 2022). "As a central regulator of cell survival in response to detrimental stimuli, SIRT1 might play a relevant role in the development and progression of endothelial dysfunction, vascular ageing, and age-related cardiovascular diseases (CVDs)." (PMID 36499460, 2022). "Endothelial upregulation of miR-34a leads to endothelial dysfunction by targeting Sirt1." (PMID 36359402, 2022). "This adipokine exhibits nicotinamide phosphoribosyltransferase (NAMPT) activity, and as an intracellular form (iNAMPT) maintains the activity of NAD-dependent enzymes, such as sirtuin 1, while the extracellular form (eNAMPT) can induce inflammation and endothelial dysfunction." (PMID 34439776, 2021). "Our results suggest that endothelial CRIF1 plays an important role in maintaining cardiac function, and that SIRT1 induction could be a therapeutic strategy for endothelial dysfunction-induced cardiac dysfunction." (PMID 33430144, 2021). "This study for the first time uncovers that GLI can relieve DR through regulation of endothelial dysfunction, inflammation, and oxidative stress via SIRT1/Notch1 pathway, suggesting that GLI may be an effective agent for the treatment of DR in clinic." (PMID 34961513, 2021). "Que may reduce oxLDL-induced oxidative damage by upregulating SIRT1 and AMPK, therefore potentially preventing oxLDL-impaired SIRT1 inhibition linked to endothelial dysfunction." (PMID 32848804, 2020). "The present study aimed to investigate the role of sirtuin 1 (SIRT1)- and transcription box-3 (TBX-3)-mediated regulation of endothelial dysfunction, given the significance of SIRT1 in glucose metabolism and the role of TBX-3 in the maintenance of cellular proliferation, senescence and apoptosis." (PMID 32627000, 2020). "Thus, the SIRT1‐eNOS‐NO axis has a protective effect against endothelial dysfunction and senescence." (PMID 33274583, 2020). "Notably, amount of evidence has proved that SIRT1 cooperates with AMPK to enhance the ability of PGC-1α to attenuate endothelial dysfunction via stimulating mitochondrial biogenesis and activating gluconeogenic fatty acid oxidation genes." (PMID 33304318, 2020). "We demonstrated that SAB could attenuate endothelial dysfunction by dramatically upregulating expression of Sirt1." (PMID 31118974, 2019). "Furthermore, studies of the secretome of SIRT1-deficient cells revealed that a key component of endothelial glycocalyx is shed, its fragment is pro-fibrogenic, whereas the aberrant composition of endothelial glycocalyx could further exacerbate endothelial dysfunction." (PMID 30298020, 2018).
endothelial dysfunction (continued). "Given the finding that neither antibiotics nor miR-204 inhibition impacted endothelium-independent vasorelaxation, it is likely that targets of miR-204, other than Sirt1, that are partly responsible for miR-204-mediated endothelial dysfunction with HFD feeding are also expressed in the endothelium." (PMID 27586459, 2016). "We then questioned whether diet-induced endothelial dysfunction is also dependent on the microbiome and triggered by miR-204-mediated downregulation of vascular Sirt1." (PMID 27586459, 2016). "SIRT1 is expressed highly in the vasculature and acts as a key regulator of vascular endothelial homeostasis by controlling angiogenesis, vascular tone and endothelial dysfunction." (PMID 24859347, 2014). "Interestingly, miR-200a, which is induced by oxidative stress, has been also demonstrated to target SIRT-1, further supporting the idea of a prominent role of miR-200 family members in oxidative stress induced endothelial dysfunction." (PMID 23975169, 2013). "In addition, there is evidence that SIRT1 protects against endothelial dysfunction by preventing stress-induced premature senescence, thereby modulating endothelial dysfunction in the progression of CVD." (PMID 23774840, 2013). "Decreased SIRT1 levels and activity may lead to increased acetylation and inactivation of eNOS in the lungs of ApoE-/- mice exposed to CS culminating endothelial dysfunction." (PMID 20663150, 2010). "Given the crucial role of SIRT1 in aging and cell senescence, we treated the etoposide‐induced senescent TSEC cells with SIRT1 activator resveratrol to observe whether SIRT1 activation could ameliorate senescence‐associated endothelial dysfunction." (PMID 39912563, 2025). "Recent studies have demonstrated that long COVID‐19 is characterized by sustained endothelial dysfunction, including microvascular damage and impaired barrier integrity, processes that SIRT1 could be uniquely positioned to address, given its well‐documented protective effects on vascular tissue." (PMID 41416347, 2025). "However, SIRT1 inhibition could suppress the protective effects of paeoniflorin on endothelial dysfunction of H2O2-induced HUVECs." (PMID 35030965, 2022). "Moreover, also sirtuin 1 (SIRT1) enzyme, a type III histone deacetylase able to regulate a plethora of intracellular signaling proteins, is implicated in ageing-related diseases, such as cardiac hypertrophy, myocardial infarct, and endothelial dysfunction." (PMID 32047577, 2020). "Therefore, upregulating SIRT1/AMPK activity might represent an effective strategy for restraining glucose-induced endothelial dysfunction." (PMID 31684006, 2019). "Moreover, as recently reported by our laboratory, the SIRT1 activator, SRT1720, may also be effective in reversing age‐associated endothelial dysfunction by reducing oxidative stress, albeit with different effects on NO." (PMID 26970090, 2016). "However, it needs to be further understood whether SIRT1 activators protect lung against cigarette smoke-induced immune-inflammation, tissue injury, senescence and endothelial dysfunction (acetylation of eNOS, adiponection, and caveolins)." (PMID 23774840, 2013). "Moreover, SIRT1 protects against endothelial dysfunction by preventing stress-induced premature senescence, thereby modulating the progression of cardiovascular diseases, and it plays an essential role in mediating the survival of cardiac myocytes under stress in vitro." (PMID 24265619, 2013). "As expected, we found that overexpression or activation of SIRT1 effectively suppressed NOX2-dependent oxidative stress, attenuated endothelial senescence, and ameliorated endothelial dysfunction triggered by K.pn EVs." (PMID 39800699, 2025).